USP45 (ubiquitin specific peptidase 45)
Diseases named in the same sentence as USP45 in open-access papers (continued):
Sharing a sentence is not in itself a finding about the gene and the disease.
tumor (4 papers, 2019 to 2025). "The results further validated and explained the conclusion that USP45 was closely associated with tumor immunity." (PMID 35836933, 2022). "In this study, we used bioinformatics to explore the expression levels and mutations of USP45 in different types of tumor and their correlation with patient prognosis, mRNA methylation, tumor heterogeneity, tumor stemness, and tumor immunity." (PMID 35836933, 2022). "In addition, we found that the expression levels of USP45 are positively correlated with tumor heterogeneity, which is an important cause of drug resistance and a challenge for precision tumor medicine." (PMID 35836933, 2022). "Promoted USP45 is upregulated in most tumor types and correlates negatively with the infiltration of NK cells, Th1 cells, macrophages, and dendritic cells." (PMID 38674024, 2024). "Promoted USP45 is upregulated in most tumor types and correlates negatively with the infiltration of NK cells in the tumor microenvironment." (PMID 38674024, 2024). "The results showed that in the majority types of tumors, the expression levels of USP45 were positively correlated with the stemness indices, indicating that USP45 was closely related to the formation of tumor stemness." (PMID 35836933, 2022). "We analyzed the correlations between USP45 and 35 types of tumor-infiltrating immune cells in tumors." (PMID 35836933, 2022). "The relationships between USP45 and mRNA methylation, tumor heterogeneity, tumor stemness, and tumor immunity were performed by Sangerbox platform and TIMER2.0 using Pearson correlation analysis." (PMID 35836933, 2022). "Through bioinformatics analysis combined with immunohistochemistry of tumor tissue microarray, we confirmed that USP45 acted as a putative oncogene in the majority types of tumors and was negatively correlated with the prognosis of tumor patients." (PMID 35836933, 2022). "At last, the protein expression levels of USP45 were detected by immunohistochemistry in tumor tissue microarrays." (PMID 35836933, 2022). "This discrepancy could be attributed to the complex tumor microenvironment, which may partially compromise the antimelanoma effects of USP45." (PMID 40788071, 2025). "Therefore, our findings suggest that USP45 can be used as a biomarker of drug effectiveness in tumor treatment." (PMID 35836933, 2022). "We analyzed the correlation between USP45 and tumor stemness indices in different types of tumors." (PMID 35836933, 2022). "And our results showed that the role of USP45 in the development of tumor maybe complex and variety." (PMID 35836933, 2022). "In the present study, we demonstrated that the expression level of USP45 in the majority types of tumors was positively correlated with the tumor stemness index, suggesting that upregulation of USP45 may promote the proliferation and metastasis of tumor cells." (PMID 35836933, 2022). "In most types of tumors, the expression of USP45 was positively correlated with many immune checkpoint molecules and immune regulators such as PD-L1, while negatively correlated with the infiltration levels of NK cells, Th1 cells, macrophages, and dendritic cells in the tumor microenvironment." (PMID 35836933, 2022). "The differential analysis filtered for processes driven by CD271 in tumor-initiating cells also revealed enrichment for the genes participating in nucleotide excision repair (NER, including damage recognition and repair factor XPC, DNA repair associated BRCA2, UBE2I, COPS7A, POLD3, USP45, RFC5)." (PMID 31118427, 2019). "Therefore, we proposed that USP45 may be involved in tumor development as a putative oncogene." (PMID 35836933, 2022). "USP45 (ubiquitin specific peptidase 45) is a de-ubiquitinase for MYC/c-Myc and correlates negatively with the infiltration of NK cells, Th1 cells, macrophages, and dendritic cells into the tumor microenvironment." (PMID 38674024, 2024). "However, no studies have yet revealed the mechanism of USP45 in tumor development." (PMID 35836933, 2022).
USP45 also shares sentences with these, for which no sentence is quoted: infection (2 papers); autism (1); breast tumors (1); brucellosis (1); colon adenocarcinoma (1); colon cancer (1); head and neck squamous cell carcinoma (1); kidney chromophobe carcinoma (1); lung adenocarcinoma (1); lung squamous cell carcinoma (1); myelogenous leukaemia (1); oral squamous cell carcinoma (1); osteosarcoma (1); ovarian carcinoma (1); renal cell carcinoma (1); Serous Ovarian Cancer (1); stomach adenocarcinoma (1); thyroid carcinoma (1); triple-negative breast carcinoma (1); uterine corpus endometrial carcinoma (1).